ZNF296 (zinc finger protein 296)
Description:
May be a transcriptional corepressor with KLF4.
Synonyms: ZFP296; ZNF342
Tractability: PROTAC: UniProt records ubiquitination sites on it.
Gene: Protein-coding gene on chromosome 19 (45,071,500 to 45,076,478, reverse strand). Ensembl gene ENSG00000170684.
Subcellular location: Nucleus
Subcellular location (Human Protein Atlas): Nucleoplasm; Centrosome
Gene Ontology:
Molecular function: protein binding; sequence-specific double-stranded DNA binding; DNA-binding transcription factor activity; RNA polymerase II cis-regulatory region sequence-specific DNA binding
Biological process: negative regulation of dendrite development; regulation of transcription by RNA polymerase II; spermatogenesis
Cellular component: nucleus
Genetic constraint (gnomAD): Loss-of-function variants: 2 observed, 9.36 expected, observed/expected ratio (o/e) 0.21, 90% interval 0.086 to 0.67. That is too few expected variants to judge how well the gene tolerates losing a copy. Missense variants: 555 observed, 647.86 expected, observed/expected ratio (o/e) 0.86, 90% interval 0.8 to 0.92. Synonymous variants: 303 observed, 267.55 expected, observed/expected ratio (o/e) 1.13, 90% interval 1.03 to 1.25.
Homologues: Orthologues: chimpanzee ZNF296 (99% identical), macaque ZNF296 (97% identical), dog ZNF296 (82% identical), guinea pig ZNF296 (80% identical), rabbit ZNF296 (80% identical), rat Zfp296 (63% identical), mouse Zfp296 (62% identical), zebrafish znf296 (31% identical). Paralogues in human: ZBTB20 (17% identical), ZBTB45 (15% identical), ZBTB16 (12% identical), PRDM1 (12% identical), PRDM14 (11% identical), HIC1 (11% identical), HIC2 (11% identical), ZNF276 (10% identical), ZNF362 (10% identical), ZNF143 (10% identical), ZNF281 (10% identical), ZNF410 (10% identical), and 24 more.
Diseases named in the same sentence as ZNF296 in open-access papers:
ZNF296 is named in the same sentence as 13 diseases in open-access papers, as found by Europe PMC text mining. Sharing a sentence is not in itself a finding about the gene and the disease. The quoted sentences say what the papers report.
breast carcinoma (1 paper, 2023). "We developed a multiplex digital droplet polymerase chain reaction (ddPCR) assay for the detection of ctDNA in breast cancer patients that targets a combination of two methylations specific for breast tissue (LMX1B and ZNF296) and one cancer specific methylation (HOXA9)." (PMID 37225860, 2023).
encephalitis (1 paper, 2025). An acute inflammatory process affecting the brain parenchyma. "The resultsindicated that in the encephalitis group, potassium channel-related gene KCNN3,cell development-related genes EMC8, DANCR, and ASPN, along with thetranscription factor ZNF296, were significantly upregulated." (PMID 40985687, 2025).
cancer (2 papers, 2017 to 2023). A tumor composed of atypical neoplastic, often pleomorphic cells that invade other tissues. "We developed a multiplex ctDNA ddPCR assay including two breast tissue specific (LMX1B and ZNF296) and one cancer specific target (HOXA9)." (PMID 37225860, 2023). "We developed a multiplex ddPCR assay targeting ctDNA with a methylation signature specific for breast tissue (LMX1B and ZNF296) and one general marker of cancer (HOXA9)." (PMID 37225860, 2023).
ZNF296 also shares sentences with these, for which no sentence is quoted: acute myeloid leukemia (2 papers); glial tumors (2); tumor (2); acute leukemia (1); gliomas (1); infection (1); oligodendroglioma (1); prostate carcinoma (1); sterility (1); teratoma (1).